FOXO3 (forkhead box O3)
Diseases named in the same sentence as FOXO3 in open-access papers (continued):
Sharing a sentence is not in itself a finding about the gene and the disease.
cancer (continued). "In mouse cancer cells, circ-Foxo3 represses cell cycle progression by the interaction with cyclin-dependent kinase inhibitor 1 (p21) and cyclin-dependent kinase 2 (CDK2), thereby blocking the roles of p21 and CDK2 in cell cycle regulation." (PMID 31519189, 2019). "Previously, we reported that rhein induced cancer cell apoptosis through FOXO3‐ and Bim‐dependent mechanisms." (PMID 29024409, 2018). "More importantly, some previous studies have indicated that CCDN1 serves as a functional downstream of FOXO3 in cancer cells." (PMID 30064475, 2018). "Transcriptional factor FOXO3 is known to be a cancer suppressor, but it also induces the high expression of CD44, a master regulator (and also a marker) of CSCs." (PMID 30563268, 2018). "Trastuzumab (Herceptin) is the first clinically approved monoclonal antibody against HER2 mutant cancer, and its antiproliferative effects have also been shown to be mediated through FOXO3 and its downstream target Survivin (BRC5) via the PI3K-Akt pathway." (PMID 29180117, 2018). "The FOXO3 protein is involved indiverse cellular and physiological processes, including cell proliferation,apoptosis, cellular responses to oxidative stress, cancer, cell cycle regulation,metabolism, and longevity (Tzivion etal., 2011)." (PMID 30088610, 2018). "Although the reported modulations seem to be opposite, the action of EGCG on FOXO3 seems to lead to cancer suppression altogether." (PMID 30563268, 2018). "In general, FOXO3 is known to inhibit cell cycle progression and to promote cell death, and it has been studied as an important inhibitor of cancer cell progression." (PMID 30514328, 2018). "Despite this, current evidence has supported the assertion that compared with other FOXO proteins, FOXO3 has a more predominant role in controlling cancer development and chemotherapeutic drug sensitivity." (PMID 29180117, 2018). "C. coccineum induces up-regulation expression of the cancer suppressor Foxo3 and its related molecules in the signaling pathway." (PMID 30261584, 2018). "Circ-Foxo3 is a highly expressed circular RNA in non-cancer cells, silencing endogenous circ-Foxo3 accelerates cell proliferation while ectopic expression of circFoxo3 hampers cell cycle progression." (PMID 28279183, 2017). "The results were comparable between the two cancer types and no sex-related differences were detectable, suggesting that the activation of AMPK/FoxO3 axis in skeletal muscle is a common event in cachectic cancer patients." (PMID 29167426, 2017). "p-FoxO3(Ser413) was primarily localized in the nucleus of control TA myofibers, and its levels considerably increased during cancer cachexia." (PMID 29167426, 2017). "It is known that up-regulation and nuclear localization of Foxo3 activates its downstream target genes, such as Bim, Bax and Puma, leading to cancer cell death." (PMID 27058618, 2016). "Our results suggest that ergosterol peroxide can inhibit oncogenic AKT and c-Myc to activate the expression of Foxo3, which in turn activates the downstream apoptosis promoting gene Puma and Bax to initiate cancer cell apoptosis pathways." (PMID 27058618, 2016). "Our results suggest that ergosterol peroxide stimulated Foxo3 activity by inhibiting pAKT and c-Myc and activating pro-apoptotic protein Puma and Bax to induce cancer cell death." (PMID 27058618, 2016). "FOXO3 is known to regulate the response to hypoxia, altering the metabolic capacity of cancer cells allowing them to adapt more readily to their environment." (PMID 28060271, 2016). "The results in Foxo3+/− mice contrast with those in Foxo1+/− mice suggest differential regulation of cancer and lifespan by DR via Foxo1 and Foxo3." (PMID 25808402, 2015). "(2007) reported functional redundancy of Foxo1, Foxo3, and Foxo4 in the regulation of lifespan and cancer in mice under the AL condition." (PMID 25808402, 2015).
cancer (continued). "The findings in Foxo3+/– mice contrast with those in Foxo1+/– mice reported previously by our laboratory suggest differential regulation of cancer and lifespan by DR via Foxo1 and Foxo3." (PMID 25808402, 2015). "The inhibition of FOXO3 is usually due to high-level activation of multiple kinases in cancer, such as Akt and IκB kinase." (PMID 25823655, 2015). "Recent studies have reported that transcription factors such as Foxo3 and Cux1 are involved in the regulation of Pik3ip1 expression in brain tissue and cancer cells." (PMID 25826393, 2015). "We found that the set of genes regulated by the 11 deregulated miRNAs was enriched for proteins that have key roles in various pathways, such as PTEN/Akt, MAPK, RhoA, FOXO3 and PDCD4 genes, which are causatively deregulated in cancer diseases." (PMID 24788655, 2014). "The proportion of RRM2B-positive cells increased as the FOXO3 levels increased (P < 0.0001), and high expression of nuclear FOXO3 coincided with RRM2B expression in cancer patients." (PMID 24947616, 2014). "It is of interest to further elucidate the molecular mechanisms governing the control of the FOXO3-mediated activation of caspase-3 protein in promoting the apoptotic signaling pathways in cancer cells." (PMID 25096914, 2014). "In the present study, we found that Sp1, which accumulated in the early stages of cancer, positively regulated miR-182 gene expression to silence FOXO3 expression and thereby promote cancer cell growth." (PMID 24519909, 2014). "LASS2 and GALNT1 were present in cancer patients, while ARHGEF39 and FOXO3 were found only in non-cancer urinary vesicles." (PMID 24458310, 2014). "Repression of FOXO3 expression in the miR-182 knockdown cells partially reversed this effect, suggesting that miR-182 promotes cancer cell growth and inhibits cancer metastatic activity by regulating the expression of FOXO3." (PMID 24519909, 2014). "The FOXO3 protein in cancer cells can be regulated by various protein modification mechanisms such as phosphorylation, acetylation and ubiquitination." (PMID 25096914, 2014). "Next, colorimetric MTS cell proliferation assays were performed to examine how RRM2B or FOXO3 expression affected the growth of cancer cells." (PMID 24947616, 2014). "During tumor development, the inhibition of FoxO3 transcriptional activity promotes cell transformation, cancer progression, and angiogenesis." (PMID 25566078, 2014). "For instance, FOXO3-induced expression of Bim, a pro-apoptotic member of the Bcl-2 family of proteins induced a caspase-dependent cell death in several types of cancers, such as in chronic leukemias, breast and gastric cancers." (PMID 32309538, 2013). "Upregulation of tumor necrosis factor related apoptosis inducing ligand (TRAIL) by increased levels of FOXO1 or FOXO3 in cancer cells, such as prostate carcinoma cells, leads to apoptosis." (PMID 32309538, 2013). "Thereby, FOXO3 provides an interesting and promising target in the PI3K-PKB pathway for cancer therapy, as its posttranslational inactivation causes apoptosis resistance." (PMID 23828551, 2013). "Deregulation of the PI3K/PKB/FOXO3 pathway was shown to be involved in cancer development and contributes to therapy resistance of different malignancies." (PMID 23828551, 2013). "Among these sites, Ser294 and Ser425 are already known to be phosphorylated by an oncogenic kinase, ERK that leads to the nuclear exclusion and degradation of FoxO3 in several cancers." (PMID 22489133, 2012). "This would provide a regulatory and therapeutic switch to control FoxO3 nuclear localization, gene regulatory activities, and cancer metastasis." (PMID 22489133, 2012). "The computational findings of this study illustrate the complex and highly dynamic role of FoxO3 and PTMs in human cancers." (PMID 22489133, 2012). "Unfortunately, the PIP3-AKT pathway is not the only reason for deregulation and nuclear exclusion of FoxO3, as observed in several cancers." (PMID 22489133, 2012).
cancer (continued). "Silencing βTrCP1 augments FOXO3 protein level, resulting in promoting cellular apoptosis in cancer cells." (PMID 20625400, 2010). "FOXO3 has been reported to regulate cancer cell stemness in previous studies." (PMID 39991565, 2025). "During cancer cell apoptosis, the circ-Foxo3 expression has been observed to markedly escalate." (PMID 39944836, 2025). "However, the SIRT1-mediated deacetylation of FOXO3 at multiple lysine residues (K242, K259, K271, K290, and K569) alters its transcriptional output and nuclear localization in cancer cells." (PMID 41008982, 2025). "It's our study come up with that propofol could inhibit cancer cell stemness and proliferation by regulation of FOXO3/SOX2 axis firstly." (PMID 39991565, 2025). "In addition, it is important to note that the role of FOXO3 in cancer is complex and context-dependent, as its activity can be influenced by various factors in different cellular environments." (PMID 39334758, 2024). "FOXO3 suppresses cancer stem cell propagation and improves disease prognosis." (PMID 38612866, 2024). "Regarding the anti-cancer mechanism, most phytochemicals induced cell cycle arrest and apoptosis in cancer cells by activating FOXO3, which led to the transcriptional up-regulation of cell cycle inhibitors (p21 and p27) and pro-apoptotic proteins (BIM, BAX, and FasL)." (PMID 39334758, 2024). "Interestingly, the results showed that FOXO3 was mainly expressed in cancer and cancer-related pathways, such as the PI3K-AKT pathway, and its main biological function was involved in the cell cycle, which was consistent with the results of SBR." (PMID 37976368, 2024). "Although FOXO3 had been reported in multiple cancers including RMS, the role of FOXO3 polymorphisms in RMS remains unclear." (PMID 38720807, 2024). "Among these, FOXO1 and FOXO3 are the most well-studied in the context of cancer." (PMID 38994962, 2024). "FOXO3 has cancer suppressive properties, while FKBP3 is carcinogenic." (PMID 37987202, 2024). "Forkhead box O3 (FOXO3), a member of the forkhead transcription factor family, contributed extensively to gene regulation by binding to and activation of enhancer regions in cancer cells." (PMID 39449966, 2024). "As far as the working mechanism of the plant extract for anti-cancer activity, researchers demonstrated that plant extract induced apoptosis in cancer cells by the activation of FOXO3 responsible for the up-regulation of pro-apoptotic BIM and BAX, as well as cell cycle inhibitors." (PMID 39334758, 2024). "However, higher levels of FOXO3 and its tumor-suppressive function are favorable in senescence and cancer therapy." (PMID 38132107, 2023). "Moreover, we also found that the expression of RASIP1 is regulated by forkhead box O3 (FOXO3), which has been reported with a cancer suppressive role in multiple tumors, including DLBCL20." (PMID 36967521, 2023). "Altogether, FOXO3 has the leverage to suppress tumorigenesis in healthy cells but may induce cytoprotective autophagy in cancer stem cells." (PMID 37190065, 2023). "Additionally, there was a significant correlation between FOXO3 and the metastasis of a number of cancers, including breast, pancreatic, and kidney cancers." (PMID 37880374, 2023). "Taken together, these findings suggested that FOXK2 and FOXO3 may be affected by opposing SIRT1‐associated molecular mechanisms under stress conditions, although the effects on cancer cell apoptosis were similar." (PMID 34866322, 2022). "circ-Foxo3 interacts with cell cycle protein cyclin-dependent kinase 2 and cyclin-dependent kinase inhibitor 1 and leads to the formation of a ternary complex, thus promoting the cell cycle progression of non-cancer cells." (PMID 36338714, 2022).
cancer (continued). "Previous studies indicated that miR-155 regulates FOXO3 expression in various cancers." (PMID 35664920, 2022). "Our research indicated the complementary roles of FOXO3 in different types of cancers." (PMID 34795388, 2022). "In addition, there is also strong evidence that FOXO3 is involved in the metastasis of multiple cancers, including the breast, kidney, and pancreatic cancers." (PMID 36555288, 2022). "By contrast, FoxO3 may increase resistance to apoptosis and cell-cycle progression, and deregulation of FoxO3 can result in cancer progression." (PMID 35884976, 2022). "Notably, AKT phosphorylating downregulates FOXO3 during cancer development, and therefore the role of FOXO3 in the regulation of senescence involving AKT-regulating circ_FOXO3 needs to be examined in cancer cells." (PMID 36230902, 2022). "Interestingly, the state of dormancy detected in several types of cancer stem cells is also maintained by FOXO3." (PMID 34832087, 2021). "Circular RNA Foxo3 (Foxo3) plays essential roles in various cancers." (PMID 34555810, 2021). "We next compared FOXO3-regulated expression programs in aging and cancer transcriptome-wide." (PMID 36303712, 2021). "Collectively, our data indicate that a mitochondrial oxPhos gene program is indirectly repressed by FOXO3 in aging and cancer, suggesting that FOXO3 functions upstream in a transcriptional hierarchy that is associated with setting metabolic states in healthy and transformed stem cells." (PMID 36303712, 2021). "As the HM450 assay has only limited genome coverage, there may be FOXO3 CpGs of interest that we missed, but most relevant CpGs, in particular, in promoter regions and related to cancer, were selected in priority for inclusion on the assay." (PMID 34943892, 2021). "Moreover, we also find subsets of genes that are deregulated exclusively in either GSCs or aged NSCs, thereby representing cancer stem cell-specific or agingspecific FOXO3 networks." (PMID 36303712, 2021). "In addition, down-regulation of FOXO3 has been shown to promote the expression of Snail and Twist-1 in several cancer cell lines." (PMID 35008549, 2021). "The human transcription factor FOXO3 (a member of the ‘forkhead’ family of transcription factors) controls a variety of cellular functions that make it a highly relevant target for intervention in anti-cancer and anti-aging therapies." (PMID 34201262, 2021). "As a critical transcription factor, FOXO3 participates in the progression of numerous cancers." (PMID 34546972, 2021). "Therefore, FOXO3-mediated regulation of cell dormancy is likely a common event among normal stem cells and cancer stem cells as an evolutionary adaptive strategy of cell quiescence." (PMID 34832087, 2021). "Functional characterization and clinical significance of circ-Foxo3 in human cancers." (PMID 33833780, 2021). "Similarly, miR-155 is involved in numerous cancer types and its upregulation in ccRCC correlates with an increase in proliferation and invasion by targeting Forkhead box O3a (FOXO3a) and E2F transcription factor 2 (E2F2)." (PMID 33918154, 2021). "Altogether, these results contribute to firmly establishing the interplay between FOXO3, autophagy and sorafenib resistance in this cancer type, supporting this new molecular mechanism that accounts for chemoresistance and opening a new therapeutic window to achieve better HCC patient outcomes." (PMID 34769197, 2021). "Furthermore, FOXO3 circular RNA has also been shown to play important regulatory roles in initiation and progression of several cancer types (breast, prostate, bladder, gastric, leukemia, etc.)." (PMID 34943892, 2021). "Accordingly, with the FOXO3 nuclear accumulation strategy against cancer cells, it may be efficient to target solitary and dormant cells that are detached from the primary cancer and disseminated to distant organs." (PMID 33795838, 2021).
cancer (continued). "In addition to their direct epigenetic action, BET proteins also coordinate an IL6-dependent AMPK nuclear signaling pathway converging on FoxO3, which contributes to cancer cachexia." (PMID 32635462, 2020). "On the other hand, FOXO3 can also upregulate the expression of DNA damage–inducible 45 (GADD45) of the DNA repair mechanism and has a role in ATM-mediated DNA damage response to prevent cancer from acquiring further mutations." (PMID 32372224, 2020). "Similarly, miR-182 suppresses both FOXO1 and FOXO3 expression levels in prostate and skin cancer, respectively, to promote cancer cell migration and invasion." (PMID 32372224, 2020). "Indeed, induction of antioxidant gene expression by FANCD2 and FOXO3 can also impact on cancer therapy resistance as radiotherapy and chemotherapeutic drugs can influence cancer treatment outcome through their modulation of ROS." (PMID 32372224, 2020). "Third, this previous study indicated that miR-490 could inhibit BC progression via regulating its target gene ZNF24, while our further experiments showed that miR-940 could promote cancer progression through regulating FOXO3." (PMID 32840296, 2020). "Down-regulation of FOXO3 is detected frequently in cancer development." (PMID 31540495, 2019). "Taken together, these results suggested that FOXO3 is an important biological factor and could be a potential target for cancer therapy." (PMID 30953521, 2019). "For LTED cells undergoing unfavorable environmental changes (e.g., estrogen deprivation), it may be inevitable that FOXO3 is upregulated so that cells become primed for apoptosis, representing the fragility of cancer." (PMID 31439835, 2019). "Moreover, recent clinical studies have shown that FOXO3 is a good prognostic marker in some cancers." (PMID 30953521, 2019). "Thereby, stress induced signaling kinases, such as JNK or MST1 that cause FOXO3 activation and nuclear accumulation also in presence of PKB signaling critically contribute to FOXO3-triggered therapy-resistance programs that protect cancer cells during therapy." (PMID 31789593, 2019). "However, FOXO3 has been reported to regulate many genes involved in cancer development, such as p21, ATR, ΔNp63, and VEGF." (PMID 31013711, 2019). "It is well‐known that the roles of FOXO3 in cancer progress are complicated." (PMID 30623608, 2019). "In HCT-15 cells, reduced transcription of cell cycle mediating genes (CCND1, PCNA, CDK2, CDKN1B), and reduced transcription of anti-apoptotic genes (BMI1, BIRC5 and BCL2), support a cancer suppressive and favorable FOXO3/FOXM1 ratio upon combined TNKSi/MEKi treatment." (PMID 30717152, 2019). "The oncogenic properties of the transcription factor FOXO3 have been reported in different cancers." (PMID 31861249, 2019). "Thus, we should consider what is the detailed relationship between JAK2, STAT3, and FOXO3 in cancer cells." (PMID 31540495, 2019). "The Foxo3 gene, belonging to the forkhead family, is one of the classes of transcription factors characterized by a forkhead DNA-binding domain, which usually considered being a cancer suppressor gene." (PMID 31533653, 2019). "The p38α pharmacological inhibitior has also been shown to be able to combine with cisplatin to decrease colony formation and viability of cancer cells and strongly increase Bax-dependent apoptotic cell death by activating FOXO3 in colorectal cancer (CRC) cells." (PMID 29180117, 2018). "Activation of FOXO3 has also been shown to reverse mitogen-activated protein/extracellular signal-regulated kinase kinase (MEK) 1/2 inhibitor AZD6244 chemoresistance in human cancer." (PMID 29180117, 2018). "Current anti-cancer drugs, including paclitaxel, doxorubicin, epirubicin, lapatinib, gefitibin, imatinib and cisplatin, have been confirmed to mediating their cytotoxic and cytostatic functions through FOXO3 and FOXM1." (PMID 29180117, 2018).